MYB (MYB proto-oncogene, transcription factor)
Diseases named in the same sentence as MYB in open-access papers (continued):
Sharing a sentence is not in itself a finding about the gene and the disease.
gastric cancer (31 papers, 2011 to 2025). A primary or metastatic malignant neoplasm involving the stomach. "miR-155 transported in gastric cancer EVs caused a decrease in c-MYB and an increase in VEGF expression, in line with the promotion of vascular growth and metastasis." (PMID 34943937, 2021). "Kaplan-Meier survival curves indicated that patients with high expression of ERCC6L and MYB had significantly longer survival than those with low expression (P < 0.05), suggesting that high expression of these two genes may be associated with improved prognosis in gastric cancer patients." (PMID 40672391, 2025). "We conducted a qPCR experiment on 7 pairs of cancerous and adjacent tissues, finding that ERCC6L and MYB expression was significantly higher in gastric cancer tissues." (PMID 40672391, 2025). "Vorinostat induced apoptosis in U937 cells by downregulation of MYB and MYBL2, and cell death upon MYB suppression in gastric cancer cells." (PMID 38835346, 2024). "Exosomal miR-130a secreted by gastric cancer (GC) cells targeted c-MYB in ECs and promoted angiogenesis in vitro and in vivo." (PMID 34966744, 2021). "Using vitro experiments, they found that the miR-130a present in exosomes derived from the SGC-7901 gastric cancer cell line induced decreased c-MYB expression and increased cell migration, proliferation, and ring formation in HUVEC." (PMID 33233600, 2020). "The CD36-BATF2/MYB trait predicts anti-PD-1 response in gastric cancer (GC)." (PMID 40672391, 2025). "Furthermore, hsa-miR-139-5p/MYB axis has been suggested to promote the proliferation, invasion, and metastasis of gastric cancer." (PMID 36061202, 2022). "Moreover, studies have shown that exosomes derived from gastric cancer (GC) cells contain miR-130a, and these exosomes carry tumor-derived stimulating factors to induce c-MYB-related angiogenesis, thereby promoting vascular growth." (PMID 35571530, 2022). "Given that hsa-miR-103a-3p responded to hypoxia and targeted argonaute 1 (AGO1) to promote angiogenesis, and EXO-miR-103a increases angiogenesis in gastric cancer targeting c-MYB, downregulation of exosomal hsa-miR-103a-3p in the BPD group is likely to suppress fetal angiogenesis." (PMID 33842462, 2021). "Similarly, gastric cancer EVs containing miR-130a were delivered to ECs, which promoted angiogenesis through targeting c-MYB." (PMID 34943937, 2021). "The relationship between EME1, Akt, and MYB in the regulation of gastric cancer was also studied." (PMID 34719326, 2021). "Exosomal miR-155 elevated growth rates of tumor cells in gastric carcinoma via c-MYB/VEGF axis." (PMID 33658392, 2021). "Therapeutically, MYB mediated EME1 activation promoted tumorigenesis in a GC cell line, orthotopic xenograft gastric cancer model." (PMID 34719326, 2021). "Here, we established an activated CD4+ memory T cells-related 3-gene prognostic model (BATF2, MYB and CD36) in gastric cancer to evaluate the activation status of CD4+ memory T cells." (PMID 37781029, 2023). "Of these 12 genes, 7 genes highly expressed in gastric cancer tissues were down-regulated (ITGB5, TYMS, MYB, APOC1, CBX5, PLA2G2A, KIF20A) and 5 low-expressed genes were up-regulated after vorinostat treatment (SCGB2A1, TCN1, CFD, APLP1, NQO1." (PMID 21931799, 2011). "Expression of ITGB5, TYMS, MYB, APOC1, CBX5, PLA2G2A, and KIF20A which is up-regulated in human gastric cancer tissues, was significantly decreased by vorinostat." (PMID 21931799, 2011). "Transcription factors MYB, MYBL2, ETV4, LEF1,TFAP2A were up-regulated in gastric cancer tissues." (PMID 25860484, 2015). "Specifically, five transcription factors MYB, MYBL2, ETV4, LEF1 and TFAP2A were up-regulated and they formed the TF-gene regulatory networks with 41 genes, 38 of which were up-regulated and 3 were down-regulated in gastric cancer tissues." (PMID 25860484, 2015). "In gastric cancer (GC), SNHG3 acts as an oncogene by modulating the miR-139-5p/MYB pathway, thereby driving proliferation, migration, and invasion." (PMID 39349640, 2024).
gastric cancer (continued). "In addition, other studies have found a negative correlation between the expression of miR-155 and MYB in gastric cancer." (PMID 34876130, 2021). "Moreover, gene expression analysis of gastric cancer identified a collection of genes (ITGB5, TYMS, MYB, APOC1, CBX5, PLA2G2A, and KIF20A) whose expression was elevated in gastric tumor tissue and downregulated more than 2-fold by vorinostat treatment in gastric cancer cell lines." (PMID 21931799, 2011).
melanoma (31 papers, 2011 to 2025). A malignant, usually aggressive tumor composed of atypical, neoplastic melanocytes. "Possible mechanisms explaining its favorable activity in melanoma are the inhibition of the transcription factor MYB and its association to aerobic glycolysis through SIX1 repression." (PMID 33003444, 2020). "In the AST group, 21 cases (54%) demonstrated isolated MYB deletion, seen in more than 40% of tumor cells, using melanoma FISH probes." (PMID 38031947, 2023). "Conversely, restoration of MYB in miR-150-overexpressed melanoma cells rescued the proliferation, migration, and invasion." (PMID 36009551, 2022). "In this study, we aimed to evaluate the diagnostic value of four-color fluorescence in-situ hybridization (FISH) probes specific to the RREB1,CCND1,and MYB genes, and centromere of chromosome 6, in distinguishing DN and melanoma." (PMID 32393283, 2020). "Discrimination between benign from malignant melanocytic lesions can also be done by utilizing fluorescence in situ hybridization (FISH), whereas especially chromosome 6 (RREB1, MYB and Cep6) is mentioned as melanoma biomarker." (PMID 30858407, 2019). "Array CGH results were further confirmed by four colour FISH experiments specific for 11q13 (specific for CCND1 gene), 6p25 (specific for RREB1 gene), 6q23 (specific for MYB gene) and centromere 6 on 27 primary melanomas." (PMID 24832207, 2014). "Similarly, miR-150 downregulates MYB to suppress proliferation, migration, and invasion of melanoma cell." (PMID 37921969, 2024). "Interestingly, we found that MYB-knockout in CRISPR screen dataset limited natural killer cell antitumor activity in melanoma but enhanced natural killer cell activity in colon adenocarcinoma." (PMID 36994664, 2023). "Moreover, MYB has been previously demonstrated as the target gene of miR-150, while miR-150 has been reported to inhibit the melanoma cell development through the down-regulation of MYB." (PMID 33407591, 2021). "In melanomas this probe set panel identified interchromsomal rearrangement in chromosome 6 with gains in 6p25 (RREB1) and loses in 6q23 (MYB), as well as common gains in 11q13 (CCND1)." (PMID 39741925, 2024). "In this study, we aimed to evaluate melanocytic tumors with spitzoid morphology using conventional melanoma FISH (RREB-1, CCND1, MYB and CEP6) and 9p21 FISH (CDKN2A) probes and compare the probe results with clinical and histopathological features." (PMID 38031947, 2023). "In the group of melanomas with spitzoid features, using melanoma FISH probes, 8 cases out of 10 (80%), demonstrated the isolated MYB gene deletion, which was detected in more than 40% of the tumor cells." (PMID 38031947, 2023). "As a result, a number of studies using conventional melanoma FISH probes (RREB1, CCND1, MYB, CEP6) have been performed in recent years." (PMID 38031947, 2023). "By conventional melanoma FISH probes, isolated MYB deletion (6q23 deletion) was the most common finding among AST and melanomas with spitzoid features (8 out of 10 in melanoma group, 21 out of 39 in AST group)." (PMID 38031947, 2023). "We analyzed 39 cases of atypical Spitz tumor (AST), 10 cases of melanomas with spitzoid features for clinicopathological data and chromosomal alterations, targeting RREB-1 (6p25), CCND1 (11q13), MYB (6q23), together with 9p21 (CDKN2A), using FISH methodology." (PMID 38031947, 2023). "Published studies have explored the combination of single or dual CTLA4/PD-1 inhibitors and MYB oncoprotein targeting DNA vaccines, SSX2 cancer antigen, PSMA prostate-specific antigen, and TRP-2 and gp100 melanoma-specific antigens." (PMID 37138873, 2023). "On the one hand, miR-150 has been described to suppress proliferation, migration and invasion of melanoma cells through inhibition of SIX1 and downregulation of MYB." (PMID 33228711, 2020).
melanoma (continued). "Significantly, the RREB1 probe, at 60% exhibited the highest sensitivity for melanoma, while the CCND1 probe and MYB probes exhibited significantly lower sensitivities at 38% and 37% respectively." (PMID 21834951, 2011). "LASSO regression analysis was used to filter TFs further in order to identify a biomarker that could predict the prognosis of patients with melanoma, based on which seven TFs (TBX21, MYB, GFI1, NFE2L3, TFAP2C, HEY2, NR2F2) were selected." (PMID 37435067, 2023). "High MYB expression is related to worse outcomes of anti-PD-1+ anti-CTLA4 treatment in melanoma, while received good outcomes of anti-PD-1 treatment in kidney cancer, melanoma, bladder cancer and glioblastoma." (PMID 36994664, 2023). "In melanoma, a study recently described cell proliferation, migration and invasion suppression by targeting the 3′-UTR region of Sine oculis homeobox 1 (SIX1), gene known in the tumorigenesis process of several cancers and also by downregulation of MYB." (PMID 36009551, 2022). "A four-probe FISH assay targeting 6p25 (RREB1), 6q23 (MYB), Cep6 (centromere 6), and 11q13 (CCND1) could discriminate between histologically unequivocal melanomas and benign nevi with a sensitivity of 86.7% and specificity of 95.4%." (PMID 34206844, 2021). "Published studies explored the combination of single or dual CTLA4/PD-1 blockade together with DNA vaccines targeting the MYB oncoprotein for colorectal cancer, SSX2 cancer antigen for sarcoma, PSMA prostate-specific antigen, P815 mastocytoma and TRP-2 and gp100 melanoma-specific antigens." (PMID 31150505, 2019).
colorectal cancer (30 papers, 2010 to 2025). A primary or metastatic malignant neoplasm that affects the colon or rectum. "Overexpression of the MYB transcription factor (+ 28.8-fold expression in knockout cells) has been associated with poor prognosis and was frequently observed in colorectal cancer (CRC)." (PMID 33515271, 2021). "MYB was associated with poor prognosis through inhibition of apoptosis in colorectal cancer." (PMID 38956026, 2024). "We measured transcriptome data of three colorectal cancer cells with scramble knockdown (C) and simultaneous knockdown of MYB, HDAC2, and FOXA2 (KD)." (PMID 39661721, 2025). "In colorectal cancer, knocking down MYB can promote the expression of miR-148a, and knockout of MYB can also partially induce apoptosis of cancer cell lines." (PMID 34876130, 2021). "Among patients with colorectal cancer, the overexpression of MYB promotes the transcription of circHIPK3 and circHIPK3 has oncogenic functions by sponging miR-7." (PMID 34876130, 2021). "Another study found that a MYB DNA vaccine in combination with an anti-PD-1 antibody or low dose cyclophosphamide effectively extended survival of colorectal cancer (CRC) bearing mice." (PMID 34876130, 2021). "Other interesting findings include MYB, which is affected by an inversion leading to a (super) enhancer-hijacking event in a colorectal cancer patient, a phenomenon that has previously been observed to occur in ACC as a result of translocations." (PMID 34257393, 2021). "In colon cancer, ginkgo flavonoids regulate the expression of miR-34a to regulate the expression of MYB, which can induce G2 phase arrest and apoptosis of colorectal cancer cells." (PMID 34876130, 2021). "Expression of MYB has been associated with sensitivity to IGF1R inhibition by CP-751,871 in lung, breast, and colorectal cancer cell lines." (PMID 27532210, 2016). "MYB's role in cancer biology is context-dependent: It drives proliferation in malignancies like colorectal cancer and embryonal rhabdomyosarcoma, yet paradoxically enhances antitumor immunity in immunogenic tumors (e.g., colon carcinoma) by activating cytotoxic T cells." (PMID 41141380, 2025). "In addition to these, pathways specific to ACC and MYB neoplastic proliferations such as, malignant neoplasms of the salivary glands, and colorectal carcinoma were also detected." (PMID 40950184, 2025). "In human colorectal cancer, miR-150 also plays a tumor-suppressive role by targeting MYB." (PMID 34876130, 2021). "We found that the states of the nodes canalized by the simultaneous perturbation of MYB, HDAC2, and FOXA2 in the Boolean GRN model were similar to the results from the in vitro knockdown experiments on the various colorectal cancer cell lines." (PMID 39661721, 2025). "Together, these results indicate that simultaneous knockdown of MYB, HDAC2, and FOXA2 can induce the reversion of colorectal cancer cells." (PMID 39661721, 2025). "Increased expression of MYB was detected in cisplatin-resistant colorectal carcinoma (CRC) cells, and treatment with a c-myb antisense oligonucleotide sensitized these resistant cells to cisplatin, indicating a significant role of MYB in cisplatin resistance of CRCs." (PMID 38835346, 2024). "In colorectal cancer (CRC), MYB is frequently over-expressed, a property that correlates with poor prognosis for patients with CRC." (PMID 25853889, 2015).
colon carcinoma (23 papers, 2010 to 2025). "Mechanistically, mutations in the intron 1 of MYB have been proposed to cause increased expression in colon cancer cells by mediating a more efficient read-through in the transcriptional attenuator region in the intron." (PMID 38542205, 2024). "First, our UV cross-linking experiments isolated a 50kDa MYB SLR polyU RNA binding activity in colon carcinoma cell line LIM1215 extracts." (PMID 25853889, 2015). "They both express the MYB oncoprotein, a protein usually over expressed in colon cancer and essential for continued proliferation and tumor cell survival." (PMID 26472027, 2015). "MYB expression correlates with poor clinical prognosis in colon tumors, and an important transcriptional regulatory region of MYB is frequently mutated in this disease." (PMID 23935942, 2013). "The involvement of MYB in epithelial tumors was first suggested by the amplification of MYB in certain colon carcinoma-derived cell lines, and by its expression in a substantial proportion of tumors." (PMID 20659323, 2010). "In colon cancer, increased levels of MYB expression also correlate with poor prognosis." (PMID 38542205, 2024). "MYB has been positively implicated in the induction of an EMT of avian embryonic neural crest cells and recently in the induction of Snail2 expression in EMT of embryonic kidney, colon carcinoma, chronic myeloid leukemia-blast crisis, and neuroblastoma cells." (PMID 24283570, 2013). "Furthermore, MYB is required for colon carcinoma cell proliferation, and is down-regulated during differentiation of these cells while, conversely, ectopic MYB expression can suppress their differentiation." (PMID 20659323, 2010). "However, there is increasing evidence for a role of MYB in colonic epithelial cell differentiation and homeostasis, and notably, in colon cancer." (PMID 20659323, 2010). "Moreover MYB expression in colon tumors correlates with poor clinical prognosis, and an important transcriptional regulatory region of MYB is frequently mutated in this disease." (PMID 20659323, 2010). "Butyrate-mediated differentiation and apoptosis were accompanied by MYB and BCL2 suppression in colon cancers, and BCL2-mediated protection from apoptosis was overcome by butyrate." (PMID 38835346, 2024). "Analyses of publicly available gene expression data sets confirmed co-expression of MYB and ATR also in AML, adult T-ALL, and colon carcinomas and adenomas." (PMID 32001675, 2020). "They showed that this treatment strategy caused cell cycle arrest at the G1 phase in female (HT-29) and male (SW480) colon cancer cells by decreasing the expression of MYC, MYB, and the PROX1 oncogenes and increasing the expression of the p21Waf1/Cip1 and p27Kip1 cell cycle inhibitors." (PMID 36412903, 2022). "Notably, analysis of global gene expression data sets revealed co-regulation of MYB and ATR also in other human malignancies such as for example AML, adult T-ALL, and colon carcinoma, indicating that the link between MYB and ATR is not restricted to ACC." (PMID 32001675, 2020). "More broadly our data suggest that targeting transcription regulation of MYB with CDK9i might be a viable approach in other MYB-dependent cancer types, since BCL-2 and/or other apoptotic regulators are also regulated by MYB in myeloid leukaemias, T-cell leukemias and colon cancers." (PMID 26812885, 2016).
acute lymphoblastic leukemia (20 papers, 2010 to 2025). Leukemia with an acute onset, characterized by the presence of lymphoblasts in the bone marrow and the peripheral blood. "Heterozygous somatic mutations have been shown to produce binding sites for the MYB transcription factor upstream of the TAL1 oncogene in acute lymphoblastic leukemia (ALL)." (PMID 40581650, 2025). "In acute lymphoblastic leukemia (ALL), heterozygous somatic mutations have been observed to create binding sites for the MYB transcription factor upstream of the TAL1 oncogene." (PMID 38374872, 2024). "This was followed by the identification of duplication of the MYB locus in paediatric acute lymphoblastic leukaemia and of genomic rearrangements involving the MYB gene in acute basophilic and myelomonocytic leukaemia." (PMID 37996430, 2023). "It is also notable that the clustering of MYB, NOTCH1, RUNX1, and FBXW7 mutations seen in this uncommon epithelial tumor ACC overlaps with frequent somatic mutations seen in human acute lymphocytic leukemia patients." (PMID 25587024, 2014). "In humans, MYB overexpression is detected in most myeloid and acute lymphoid leukemia." (PMID 27533466, 2016). "MYB is a proto-oncogene which is overexpressed in most human myeloid and acute lymphoid leukemias." (PMID 26472107, 2015). "Knockdown of MYB sensitized acute lymphoblastic leukemia (ALL) cells to doxorubicin and 6-mercaptopurine by downregulating anti-apoptotic BCL2." (PMID 40725394, 2025). "In addition, the suppression of MYB in acute lymphoblastic leukemia (ALL) cells transfected with doxycycline-regulated lentiviral sh-c-Myb sensitized these cells to treatment with DNA-targeting drugs (doxorubicin and the antimetabolite 6-mercaptopurine) by downregulation of anti-apoptotic BCL2." (PMID 38835346, 2024). "MYB has been shown to be over-expressed in patients with T-cell acute lymphoblastic leukemia (T-ALL)." (PMID 35408829, 2022). "MYB has also been implicated in the development of T-cell acute lymphoblastic leukemia (T-ALL), due to duplication or translocation affecting the MYB locus." (PMID 35406726, 2022). "Mansour and colleagues dissected the molecular mechanisms by which a short 12‐bp insertion approximately 8 kbp upstream of the TAL1 oncogene introduces novel binding sites for the transcription factor MYB, and establish a new super‐enhancer in a subset of acute lymphoblastic leukemia (ALL) cases." (PMID 33502116, 2021). "In T‐cell acute lymphoblastic leukemia (T‐ALL), specific non‐coding mutations upstream of the TAL1 oncogene are capable of generating a self‐sustaining transcriptional loop, which involves several T‐ALL transcription factors such as MYB, GATA3, RUNX1 and TAL1 itself." (PMID 27756687, 2017). "It was demonstrated that transfection with these miRNAs induces a 30% down-regulation of wild-type MYB mRNA level in a T-cell acute lymphoblastic leukemia cell line, whereas this treatment does not decrease levels of the chimeric transcripts in ACC cells." (PMID 27533466, 2016).